INS (insulin)
Diseases named in the same sentence as INS in open-access papers (continued):
Sharing a sentence is not in itself a finding about the gene and the disease.
Sepsis (continued). "Although the role of intensive insulin therapy in patients with severe sepsis remains uncertain, insulin may have other beneficial effects in this patient population." (PMID 19216780, 2009). "There were no other factors that might have caused the DKA in Cases 1 or 2, such as sepsis or nonadherence to insulin." (PMID 40546578, 2025). "After performing univariate logistic regression analysis, we identified the confounding variables related to sepsis risk in this analysis, including cardiogenic shock, respiratory failure, SAPSII, SOFA, GCS, CCI, SPO2, platelet, total bilirubin, vasopressor, antibiotics, and insulin (P < 0.05)." (PMID 40773463, 2025). "Enrichment of the Ribosome suggests a compensatory enhancement of protein synthesis under cellular stress, a phenomenon that may occur in both pancreatic β-cells in T2DM (in response to insulin secretion load) and immune cells in sepsis (in response to pathogen attack)." (PMID 41050938, 2025). "It is yet unclear how diabetes affects sepsis-related mortality, despite the widely held view that inadequate glycemic management contributes to a significant number of severe infections, insulin, metformin, and thiazolidinediones may lower the incidence and fatality rate of sepsis." (PMID 38146555, 2023). "We came up with a hypothesis that exercise may serum insulin concentrations during sepsis." (PMID 34493741, 2021). "However, the molecular mechanism involved in the improvement of sepsis outcome by insulin remains unclear." (PMID 33679687, 2020). "This approach will comprehensively evaluate whether treatment with insulin plays a protective role in host cells receiving the inflammatory stimulators, and further establish the potential of insulin as a new therapeutic agent against sepsis." (PMID 33679687, 2020). "In addition, serum insulin could possibly be elevated in babies with sepsis in reaction to the effect of stress and other counter-regulatory hormones like glucagon and cortisol." (PMID 32637004, 2020). "Furthermore, insulin influences lipid metabolism and decreases lipid peroxidation during sepsis." (PMID 28428961, 2017). "Pre-existing insulin treatment did not affect any of the plasma host response biomarkers or the blood genomic response in our cohort, possibly due to the more profound alterations caused by the sepsis response in both groups." (PMID 27495247, 2016). "It is not clear whether protection against acute pancreatitis produced by insulin is due to a direct effect on acinar cells, modification of the systemic inflammatory response or due to tight glycaemic control, which reduces the chance of sepsis." (PMID 24993827, 2014). "Interestingly, insulin treatment markedly increased the PGE2 levels in diabetic rats with sepsis." (PMID 25398720, 2014). "However, it should be noted that the insulin-dependent mechanism of leucine-enhanced protein synthesis is associated with increased phosphorylation of S6k and 4E-BP1 and that the stimulating effect of leucine on protein synthesis is impaired in animal sepsis." (PMID 21483870, 2011). "Furthermore, the recently finished Volume Substitution and Insulin Therapy in Severe Sepsis trial, a randomised multicentre trial designed to assess the efficacy and safety of intensive insulin therapy in patients with severe sepsis and septic shock, was stopped early for safety reasons." (PMID 18799004, 2008). "Sepsis is a common precipitant of DKA and EDKA, as systemic inflammation exacerbates insulin resistance, lipolysis, and ketogenesis." (PMID 40741547, 2025). "Protein tyrosine phosphatase 1B (PTP1B) modulates endothelial nitric oxide synthesis and insulin signaling during SIMD progression, with its expression levels strongly correlating with sepsis-induced organ failure severity (NCT02295514)." (PMID 41256846, 2025).
Sepsis (continued). "Our findings suggest that patients who use insulin are at increased risk of sepsis, which may be primarily explained by the fact that insulin therapy typically indicates more severe or advanced cases of T2DM, placing these patients at inherently higher risk of infections and sepsis." (PMID 40863575, 2025). "However, the effects of sepsis on insulin’s signal transduction pathway are unknown." (PMID 37550630, 2023). "Thus, inflammation/CLP/sepsis-induced increases in endogenous levels of epinephrine, glucagon, cortisol, and pro-inflammatory cytokines and treatments such as norepinephrine administration may limit the ability to assess the effects of insulin." (PMID 37550630, 2023). "In line with the previous findings, we found a significant correlation of chemerin with the severity scores APACHE II and SOFA and also with glucose, insulin and HOMA-IR at sepsis onset." (PMID 35204801, 2022). "We also found a significant positive correlation of chemerin with glucose, insulin and HOMA-IR at sepsis onset." (PMID 35204801, 2022). "Physiological derangements at presentation include a marked stress response, gut dysfunction, insulin resistance, fluid shifts, SIRS and sepsis with varying degrees of organ dysfunction." (PMID 33677649, 2021). "In sepsis, the role of CTRP1, with regard to its critical role in regulating systemic energy homeostasis and insulin sensitivity, is currently not fully understood." (PMID 31083558, 2019). "It is well known that insulin tolerance is impaired in severe conditions, such as ARDS, severe sepsis, and severe burn." (PMID 29950925, 2018). "In 2001, a randomized controlled trial showed that intensive treatment with insulin (80–110 mg/dL) resulted in a lower hospital mortality in the surgical ICU, which was attributed to a reduction of mortality in patients with sepsis." (PMID 25136614, 2014). "When insulin was injected by 4.8 mU/(kg∙min) for 6 hours, we found that H2O2 were decreased sigificantly in cortex (vs. sepsis group, p < 0.05)." (PMID 25093012, 2014). "When insulin was injected at 4.8 mU · kg-1 · min-1 for 6 h, the IL-6 and TNF-a levels decreased significantly in the cortex, hypothalamus, and hippocampus (vs. sepsis group, p < 0.05)." (PMID 25093012, 2014). "When insulin was injected at 4.8 mU · kg-1 · min-1 for 6 h, IL-6 and MDA levels decreased significantly in all brain regions (vs. sepsis group, p < 0.05)." (PMID 25093012, 2014). "Intensive insulin therapy (IIT), maintaining blood glucose levels within a specific range, offers benefits such as improved mitochondrial function, enhanced insulin sensitivity, and reduced infection/sepsis incidence." (PMID 39830385, 2024). "Insulin levels transiently fall during sepsis due to increased clearance rather than decreased secretion, increasing energy substrate availability." (PMID 37144447, 2023). "Otherwise, particularly insulin-resistant and septic patients were comparable in that regard, and after stratification, we found a significant increase in betatrophin/ANGPTL8 in subjects with concurring sepsis and hypertriacylglyceridemia." (PMID 36551906, 2022). "In animal models of sepsis, intestinal glucose can induce the decrease of intestinal glucose levels and blood sugar, and GIP promotes insulin secretion, reduces glucagon secretion, increases insulin secretion, weakens the systemic inflammatory response, and improves hemodynamics." (PMID 34335269, 2021). "Although the number of septic patients was not reported at baseline, intensive insulin therapy reduced episodes of nosocomial septicaemia of about 46% and the proportion of patients requiring prolonged antibiotic therapy." (PMID 33973089, 2021). "Immunomodulatory effects of both insulin and non-insulin glucose-lowering agents have been extensively documented, and their beneficial impact in diabetic patients with sepsis has been suggested." (PMID 33973089, 2021).
Sepsis (continued). "Compared to controls, subjects with sepsis exhibited elevations in methylated INS and CHTOP-817 DNA levels but not the corresponding unmethylated DNA levels." (PMID 32736653, 2020). "In the present study, we explored the immuno-modulatory role of insulin in sepsis and demonstrated that insulin inhibited the inflammatory response by reducing the oligomerization of the ASC, leading to attenuation of inflammasome activation during sepsis." (PMID 33679687, 2020). "Diabetic patients also represent an additional challenge because insulin treatment is not effective during sepsis." (PMID 29780390, 2018). "More interestingly, we found that POMC knockdown had no significant impact on the activities of hepatic enzyme markers (ALT and AST) and NF‐κB pathway with or without insulin treatment in sepsis rats." (PMID 29285858, 2018). "mRNA expression of Pck1 and G6pc further confirmed that hepatic GNG was inhibited in sepsis rats, which was partly restored by insulin treatment though the change of Pck1 was not significant." (PMID 29285858, 2018). "Many studies, including the Efficacy of Volume Substitution and Insulin Therapy in Severe Sepsis (VISEP) trial, Scandinavian Starch for Severe Sepsis/Septic Shock (6S) trial, and Crystalloid vs. Hydroxy-Ethyl Starch Trials (CHEST) were conducted to compare the efficacy of each in septic patients." (PMID 27081589, 2016). "Because the result in this study showed that the level of insulin in LPS group did not alter; thus, in the early stage of sepsis, GLUT4 protein translocation by noninsulin dependent pathway can be actually a mechanism for glucose metabolism in skeletal muscle." (PMID 25097857, 2014). "However, when insulin was injected at 4.8 mU · kg-1 · min-1 for 6 h, the serum S100 and NSE levels significantly decreased (vs. sepsis group, p < 0.05)." (PMID 25093012, 2014). "Here we can show that in a mouse model of insulin hypersensitivity induced by the deletion of the PI3K antagonist PTEN, specifically in hepatic tissue, significant protection is conferred in murine models of lethal endotoxemia and sepsis." (PMID 23825606, 2013). "In addition to sepsis-specific therapies, general measures for ICU patients such as ventilation with low tidal volumes and glucose control with intravenous insulin therapy were also routinely implemented during the second period." (PMID 23601847, 2013). "Intensive insulin therapy resulted in a significant reduction of mortality (10% versus 20%; P = 0.005), exclusively in those patients requiring ≥5 days of ICU care with multiorgan failure and sepsis." (PMID 23209941, 2012). "In the present study, the median value of individual mean BG levels (177.3 mg/dl (148.8 to 205.6 mg/dl)) suggested that BG was not well controlled, and insulin treatment was inadequate in patients with sepsis." (PMID 23062226, 2012). "Comparison of clinical characteristics and glucose, cortisol, and insulin indices of three ICU groups: survivors without sepsis (Group 1), survivors with sepsis (Group 2) and non-survivors (Group 3)." (PMID 23056354, 2012). "The mechanisms of insulin resistance in the clinical setting of severe sepsis are numerous and not exactly understood." (PMID 19545363, 2009). "In this report, children with meningococcal sepsis had higher peak BG levels and low insulin levels compared with children with meningococcal bacteraemia without sepsis." (PMID 19245691, 2009). "Inflammation-insulin resistance crosstalk and altered innate immunity in MASLD may amplify cholestatic responses to sepsis, hypoperfusion, and parenteral/enteral nutrition—typical ICU exposures—without necessarily increasing hepatocellular injury rates at 72 h." (PMID 41470094, 2025). "In terms of antidiabetic medications, insulin use was markedly higher among patients with sepsis (7.3% vs. 2.9%, p < 0.001), while none of the sepsis patients received GLP-1 receptor agonists, compared with 4.1% in the non-sepsis group (p = 0.004) who received them." (PMID 40863575, 2025).
Sepsis (continued). "However, since hypoglycemia is harmful to septic patients, glycemic control by intensive insulin therapy is not the current trend in sepsis management, and a typical target blood glucose range is set at 144–180 mg/dL (Recommendation 69)." (PMID 38658435, 2024). "However, when stratified according to the occurrence of sepsis, the nonseptic patients showed lower insulin requirements with the glucose–fructose–xylitol regime (37 ± 17 vs. 44 ± 17 U/day, p = 0.026)." (PMID 31261760, 2019). "Furthermore, the knocking down experiment by a central lentiviral approach indicated that hypothalamic POMC expression contributed to the enhancement of hepatic GNG in sepsis rats, but was not required for the anti‐inflammatory action of insulin." (PMID 29285858, 2018). "Interestingly, during the hypoglycemic stages of sepsis, glucose uptake in macrophage-rich tissues remains elevated and is independent of changes in glucose and insulin." (PMID 30618812, 2018). "Indeed, no significant changes in glucose blood were observed while sepsis rats received insulin treatment." (PMID 29285858, 2018). "Insulin, which has now been confirmed to be the major bioactive component of GIK, can decrease pyruvate production and glycolysis and increase glycogen synthesis, which may result in reduced production of lactate during sepsis." (PMID 28428961, 2017). "This suggests that intensive insulin therapy does not reduce the severity of sepsis." (PMID 25136614, 2014). "During sepsis, the heart shows little or no insulin resistance and lowers its glucose consumption." (PMID 25177798, 2014). "It is noteworthy that insulin treatment has a positive effect in diabetics by restoring the immune response to infections and a negative effect by abolishing the lung protection to sepsis as we showed here." (PMID 25398720, 2014). "In a study by Van den Berghe and coworkers, in patients who received aggressive insulin therapy to maintain serum glucose ≤110 mg/dL, cardiac surgical mortality was only reduced in those patients receiving more than 3 days of ICU care and in those with multiorgan failure and sepsis." (PMID 23209941, 2012). "However, no reports on the influence of insulin on theUb-proteasome system under sepsis currently exist." (PMID 21639905, 2011). "However, we found a close inverse correlation of ghrelin with serum glucose and insulin only in the subgroup of non-sepsis patients, but not in sepsis patients." (PMID 20500817, 2010). "However, this dose may not be suitable for severe DKA, particularly in insulin-resistant adolescents, obese individuals, or those with concurrent sepsis." (PMID 41227190, 2025). "Therefore, the liver protective and anti‐inflammatory effect of insulin in sepsis rats could be independent of hypothalamic POMC." (PMID 29285858, 2018). "This does not, however, indicate that insulin therapy may not have beneficial effects in sepsis." (PMID 28768529, 2017). "Thus, a co-ordinated and negative and positive feedback regulatory action among insulin, Δ6 and Δ5 desaturases, various PUFAs and their pro- and anti-inflammatory bioactive lipids and cytokines is needed to control infection and recover from sepsis and ARDS." (PMID 27887602, 2016). "However, under sepsis conditions, whether insulin also inhibits the expression of the Ub is not currently known." (PMID 21639905, 2011). "Here, we demonstrate that youth with severe systemic inflammation/illness (sepsis) exhibit elevated methylated CHTOP-817 and INS, without changes in corresponding unmethylated DNA levels." (PMID 32736653, 2020). "In the present work we found evidence that the milder sepsis-induced ALI in diabetics is accompanied by lower fibroproliferation and this was increased to non-diabetic levels with insulin treatment." (PMID 25398720, 2014). "Different roles of FoxO1 and FoxO3 in insulin and AMPK signaling have been suggested in previous in vitro non-muscle cell studies and in rat sepsis-induced muscle wasting." (PMID 21483870, 2011).
Sepsis (continued). "Sepsis is a life-threatening clinical syndrome accompanied by severe systemic metabolic disorders, and pathological white adipose tissue (WAT) browning is a core driver that exacerbates negative energy balance, skeletal muscle dysfunction and insulin resistance." (PMID 42282442, 2026). "This hypothesis is further supported by our finding of a close inverse correlation of ghrelin with serum glucose (r = -0.369, P = 0.018) and insulin (r = -0.406, P = 0.019) as important markers of carbohydrate metabolism in non-sepsis patients at admission to the ICU, but not in sepsis patients." (PMID 20500817, 2010).